IRF4 (interferon regulatory factor 4)
Diseases named in the same sentence as IRF4 in open-access papers (continued):
Sharing a sentence is not in itself a finding about the gene and the disease.
diffuse large B-cell lymphoma (29 papers, 2012 to 2025). "MUM1/IRF4 has been shown to have a crucial role in lymphoid malignancy and is a well-known biomarker of activated B-cell like diffuse large B-cell lymphoma." (PMID 40973845, 2025). "Len and Pom also inhibit NF-κB in diffuse large B cell lymphoma (DLBCL) and MM, and this, along with effects on IRF4, is associated with inhibition of cell growth and cellular toxicity." (PMID 28881567, 2017). "LBCL-IRF4 is a very infrequent neoplasm accounting for 0.05% of diffuse large B-cell lymphomas; it primarily affects children and young adults with a median age of 12 years and is characterized by a strong expression of IRF4/MUM1 and frequent IRF4 rearrangement." (PMID 34283060, 2021). "Apart from these functions during normal lymphopoiesis, IRF4-dependency is a characteristic of various hematopoietic malignancies, including multiple myeloma, diffuse large B-cell lymphoma (DLBCL) subtypes, or T-cell lymphoma entities." (PMID 37935654, 2023). "Similarly, it was also shown that down regulation of IRF4 could be induced in ABC diffuse large B cell lymphoma after BTK inhibition using ibrutinib." (PMID 29348877, 2017). "IRF4 rearrangement in diffuse large B-cell lymphomas (DLBCL) is uncommon." (PMID 39897193, 2025). "IRF4 is an essential survival factor for T1 EBV-transformed LCLs, as well as many activated diffuse large B cell lymphomas (DLBCLs)." (PMID 35472072, 2022). "Expressions of Bcl-6, CD10, and IRF4 are used in immunohistochemical stains to separate diffuse large B cell lymphomas into GC and non-GC subtypes." (PMID 26829983, 2016). "Notably, sets of genes upregulated after IRF4 and/or SPIB knockdown in activated B-cell (ABC)-type diffuse large B-cell lymphoma (DLBCL) cell line (IRF4_ABC_REPRESSED_ALL and IRF4_SPIB_ABC_REPRESSED_ALL; NES = 1.38 and 1.55; FDR q-value = 0.17 and 0.07) were also significantly enriched in NMZLs." (PMID 32585984, 2020). "Biopsy and pathology analysis revealed a diffuse large B-cell lymphoma (DLBCL), with positive staining for CD20, CD79a, BCL2 and BLC6, but negative for CD10; 30% of the cells were positive for MIB-1 but MUM1 (IRF4) staining was negative, suggesting a germinal center-type lymphoma." (PMID 39110273, 2024).
B-cell lymphomas (27 papers, 2012 to 2025). "The enriched pathways predominantly include those associated with ABC-type DLBCLs, B-cell lymphomas with plasmacytic differentiation, and activated B-/myeloma cells downstream of IRF4/MUM1 transcriptional activity." (PMID 41008822, 2025). "Emerging B-cell lymphomas with recurrent gene alterations such as IRF4 rearrangement and 11q gain/loss chromosomal alterations will be reviewed." (PMID 39707053, 2025). "Herein, we present a case of classic follicular lymphoma exhibiting a purely follicular growth pattern with low‐grade morphology, but with high MUM1 expression and IRF4 rearrangement, thus broadening the spectrum of B‐cell lymphomas associated with IRF4‐R." (PMID 39415926, 2024). "This case broadens the spectrum of B‐cell lymphomas associated with IRF4 rearrangement by demonstrating a small B‐cell lymphoma with this genetic feature." (PMID 39415926, 2024). "Since it has been found that IRF4 rearrangement can occur in some other aggressive B‐cell lymphomas as well, especially those which are associated with MYC or BCL2 rearrangement, mainly in adults." (PMID 37081786, 2023). "A pool of important genes involved in B-cell development, oncogenesis, cell cycle regulation, and cell death including BATF, LIMD1, CFLAR, PIM2, and CCND2 are common signatures associated with IRF4 in non-Hodgkin B cell lymphomas." (PMID 25207815, 2014). "Therefore, Spi-B may be involved in a unique regulatory network where it is more frequently associated with IRF4 in B cell lymphomas, and may be directed to these sites by IRF4 or function to alter IRF4 occupancy within the genome." (PMID 25765478, 2015). "Rearrangements of IRF4 have been identified in low-grade B-cell lymphomas, plasma cell neoplasms, and T-cell lymphoproliferative disorders." (PMID 39897193, 2025). "The first case was reported in 2001, showing IGH translocation involving 6p25 (IRF4) in a screening of 173 patients with B-cell lymphomas." (PMID 39897193, 2025). "In the most recent publication from the World Health Organization (WHO) Classification of Tumours of Haematopoietic and Lymphoid Tissues, one B cell lymphoma entity with interferon regulatory factor (IRF)‐4 rearrangement has been recognized." (PMID 39415926, 2024). "WHO-HAEM4R included large B-cell lymphoma with IRF4 rearrangement, a de novo B-cell lymphoma with a follicular and/or diffuse pattern, strong expression of IRF4/MUM1 and a favorable prognosis, as a provisional entity." (PMID 38978094, 2024). "LBCL, IRF4+ hence represents a previously unrecognized subset of B‐cell lymphomas with distinctive clinicopathologic characteristics and molecular alterations." (PMID 37081786, 2023). "IRF4 is a surrogate immunohistochemical marker for the “activated B cell” subtype of DLBCLs and is also an essential survival factor for activated B cell lymphomas in humans." (PMID 30125329, 2018). "For example, previous investigation indicated that in contrast to human DLBCL, BCL6 and MUM1/IRF4 rarely expressed in canine B-cell lymphoma." (PMID 28069005, 2017). "Despite being a defining feature of LBCL‐IRF4‐R, IRF4 rearrangement is not exclusive to this subtype, as it can also occur in other aggressive B‐cell lymphomas, particularly those associated with MYC or BCL2 rearrangements." (PMID 39415926, 2024). "However, with the updated understanding of WR, these cases would best fit the new entity classification of large B-cell lymphomas with IRF4 rearrangement." (PMID 28086220, 2017). "Next, we analyzed the gene expression profiles for IRF4 expression in different types of B cell lymphomas with a total of 336 samples which include 36 cancer cell lines (10.7%), 125 experimentally manipulated B cell lines (37.2%), and 25 normal B cell samples (7.4%)." (PMID 25207815, 2014).
B-cell lymphomas (continued). "Interestingly, high levels of IRF4 protein exist in Epstein-Barr virus (EBV)-transformed cells and associated B-cell lymphomas with Type 3 latency, as well as in Human T-cell Leukemia Virus-1 (HTLV1)-infected cell lines and associated Adult T-cell Leukemia (ATL)." (PMID 25207815, 2014). "To analyze IRF4-C99R functionality, we generated tetracycline (Tet)-inducible IRF4-C99R and IRF4-WT expressing bulk cultures of BJAB B-cell non-Hodgkin lymphoma cells, which express endogenous IRF4 only at a low level." (PMID 37935654, 2023). "To further characterize the subtype of the B cell lymphoma in study, we used antibodies against subtype markers, Bcl-6, CD10 and IRF4 for immunohistochemistries." (PMID 22848504, 2012). "BCL2 and/or MYC rearrangements are absent and aggressive B-cell lymphomas with IRF4 rearrangement, harboring also MYC and/or BCL2 rearrangements, are excluded from this entity." (PMID 39684922, 2024). "This entity does not include aggressive B-cell lymphomas with IRF4 rearrangements that also harbor BCL2 and/or MYC rearrangements." (PMID 36460764, 2023). "Bcl-6, IRF-4 (MUM-1) and Bcl-2 were often detected in patients with HBsAg-positive B-cell NHL." (PMID 31120924, 2019). "Since the phosphorylation of IRF4 detected in ABC-DLBCL was decreased by Y-27632, we directly investigated whether ROCK activation was differentially regulated in distinct subtypes of B-cell lymphomas." (PMID 32753663, 2020). "Moreover, the cells were found to be positive for CD20, BCL-2, BCL-6 and IRF-4 (Mum-1) and be negative for CD10 and CD5 by Immunofluorescence, which was similar to the immunophenotypic profiles of the majority of HBsAg-positive B-cell NHL patients." (PMID 31120924, 2019).
Obesity (26 papers, 2015 to 2025). Accumulation of substantial excess body fat. "Expression of IRF4 in BAT is strongly correlated with serum MSTN levels, with loss of IRF4 causing obesity, decreased exercise capacity, and increased serum MSTN." (PMID 39340593, 2025). "In this context, high levels of Camp and Lcn2 are associated with muscle degeneration and can be implicated in Duchenne muscular dystrophy; Clstn3 is associated with obesity risk; and Irf4 knockout mice show better exercise capacity." (PMID 40002138, 2025). "The IRF4 gene, which is significantly downregulated in periodontitis, confers resistance to obesity and enhances insulin sensitivity following specific knockout in mice." (PMID 40606607, 2025). "Irf4 influences exercise capacity, obesity, and insulin resistance, with increased expression observed in obese individuals." (PMID 40002138, 2025). "IRF4 plays an important role in the development of obesity and insulin resistance and regulates skeletal muscle amino acid metabolism." (PMID 40002138, 2025). "MDSCs have been reported in autoimmunity, pregnancy, obesity and infectious diseases, but the effect of IRF4 on MDSCs in S. japonicum infection has been rarely reported." (PMID 39609883, 2024). "We identify an important network involving Tlr9, Irf4 and Il-10 interconnecting metabolic homeostasis, with the function of B and T cells, and gut microbiota in obesity." (PMID 38762479, 2024). "MDP and mifamurtide mitigate obesity and insulin resistance via suppressing the interferon regulatory factor 4 (IRF4) due to activation of NOD2, whereas iE-DAP and its derivatives exhibits the opposite effect." (PMID 37013853, 2023). "Our results show that adipocyte IRF4 is required for the postbiotic MDP to improve blood glucose during endotoxemia or obesity in male mice." (PMID 35993451, 2022). "Taken together, our data support a role for adipocyte IRF4 in mediating the glucose‐lowering effects of the postbiotic MDP during diet‐induced obesity in male mice." (PMID 35993451, 2022). "Conversely, selective ablation of IRF4 driven by the UCP1 promoter was associated with reduced energy expenditure, increased predisposition to diet induced obesity and cold intolerance." (PMID 26973598, 2016). "Analysis of brown fat-specific IRF4 transgenic mice demonstrated that IRF4 is sufficient to increase energy expenditure and to protect from diet-induced obesity." (PMID 26973598, 2016). "Furthermore, Irf4-/- adipose tissue macrophages enhanced M1 polarization, indicating that IRF4 negatively regulates inflammation in diet-induced obesity." (PMID 39384770, 2024). "IRF4 codes for the interferon regulatory factor 4 and has a diverse role as repressor of adipogenesis and as a negative regulator of the inflammatory response to obesity through M2 macrophage polarization." (PMID 37672078, 2023). "Here, we measured how MDP injection altered glucose tolerance and adipose tissue inflammation during low‐level endotoxemia and high fat diet (HFD)‐induced obesity in male and female adipocyte‐specific IRF4 knockout mice (AdipoIRF4fl/fl) compared to WTfl/fl mice." (PMID 35993451, 2022). "Muramyl dipeptide mitigates obesity-induced insulin resistance by targeting nucleotide-binding oligomerization domain-containing protein 2 (NOD2) and interferon regulatory factor 4 (IRF4)." (PMID 38201117, 2023). "Adipocyte IRF4 was required for the blood glucose‐lowering effects of MDP during endotoxemia and HFD‐induced obesity in male mice." (PMID 35993451, 2022). "While it has been suggested that the transcription factor, interferon regulatory factor 4 (IRF4), is involved in the MDP-NOD2-induced insulin sensitizing effects during obesity, the precise mechanism of MDP’s beneficial effects has yet to be elucidated." (PMID 32722085, 2020). "Expression of interferon regulatory factor 4 (IRF4) is induced by cold in both BAT and WAT and overexpression of IRF4 in BAT and WAT leads to enhanced thermogenesis and resistance to HFD-induced obesity." (PMID 26322018, 2015).
Obesity (continued). "Here, we tested if adipocyte IRF4 was required for MDP‐induced changes in blood glucose control and adipose inflammation in male and female mice during low‐level endotoxin stress or diet‐induced obesity." (PMID 35993451, 2022). "Our findings identify that DHM prevents obesity by inducing the browning of WAT through the upregulation of IRF4/PGC-1α, which may have potential therapeutic implications for the treatment of obesity." (PMID 35690863, 2022). "Additionally, the muramyl dipeptide from bacterial cell wall was a beneficial postbiotic which could mitigate obesity-induced insulin resistance by targeting nucleotide-binding oligomerization domain-containing protein 2 (NOD2) and interferon regulatory factor 4 (IRF4)." (PMID 34579087, 2021). "Mice lacking IRF4 in BAT are vulnerable to cold exposure and obesity and insulin resistance during high-fat diet (HFD), while mice that overexpress IRF4 in BAT have opposite phenotypes." (PMID 39093510, 2024).
Stroke (21 papers, 2014 to 2025). Sudden impairment of blood flow to a part of the brain due to occlusion or rupture of an artery to the brain. "While IRF5 CKO led to a decrease only in IL-1β expression after stroke, IRF4 CKO caused up-regulation of both IL-1β and TNF-α in ischemic microglia." (PMID 35963621, 2022). "The present study focused on two X chromosome escapee genes, Kdm6a and Kdm5c, and investigated their epigenetic modulation of IRF5/IRF4 via demethylation of H3K27Me3/H3K4Me3 in aged microglia after stroke." (PMID 39399684, 2024). "We found aged microglia express higher levels of IRF5 and lower levels of IRF4 than young microglia after stroke." (PMID 35963621, 2022). "Our previous study has found interferon regulatory factor 5 (IRF5) and 4 (IRF4) regulate neuroinflammation in young stroke mice." (PMID 35963621, 2022). "Irf4 is expressed by multiple brain cell types, including neurons and microglia, and plays a protective role in response to stroke." (PMID 36550567, 2022). "In this study, we used transgenic mouse models to specifically study the effect of conditional knockout (CKO) of IRF4 or IRF5 in microglia on post-stroke inflammation and outcomes." (PMID 35963621, 2022). "IRF5 CKO aged mice had improved stroke outcomes; whereas worse outcomes were seen in IRF4 CKO vs. their flox controls." (PMID 35963621, 2022). "For anti-inflammatory cytokines, a relatively homogenous pattern was seen; IRF5 CKO induced a significant increase in both IL-4 and IL-10 levels, and IRF4 CKO caused significant reduction in IL-4 and a decrease trend in IL-10 level, in stroke groups." (PMID 35963621, 2022). "Unsurprisingly, a number of studies have previously reported that IRF4 can improve neuronal survival, neuroinflammation, and stroke outcomes." (PMID 35091544, 2022). "IRF5 and IRF4 signaling drives microglial pro- and anti-inflammatory response respectively; microglial IRF5 is detrimental and IRF4 beneficial for aged mice in stroke." (PMID 35963621, 2022). "In the present study, we further investigated microglial IRF5 and IRF4 expression in young vs. aged mice after stroke with flow cytometry." (PMID 35963621, 2022). "Recent studies have demonstrated that IRF5 and IRF4 expression in microglia exhibited a “see-saw” pattern and corresponded with pro-and anti-inflammatory profiles, respectively, after stroke." (PMID 33317034, 2020). "Secondly, IRF4 expression corresponds to M2 microglial polarization, which is consistent with the anti‐inflammatory state at the late phase of stroke." (PMID 29131464, 2018). "IRF5/4 mRNA ratio also significantly increased at 3 days of stroke; IRF4/5 mRNA ratio showed a trend of transient increase at 24 h which significantly decreased at 3 days and significantly increased at 10 days after stroke." (PMID 29131464, 2018). "Our results revealed that the IRF5 mRNA level in sorted microglia increased at 3 days of stroke; whereas IRF4 mRNA level exhibited biphasic increases, with a transient rise at 24 h and a peak at 10 days." (PMID 29131464, 2018). "Ongoing studies in the laboratory are investigating contributions of IRF5/4 signaling from microglia and/or infiltrating monocytes on stroke outcome with IRF4/5 conditional knockout (CKO) mice and bone marrow chimera mouse models." (PMID 29131464, 2018). "At 24 h of stroke, IRF4 mRNA significantly increased followed by a significantly lower level at day 3 compared to the sham group; at day 10, IRF4 mRNA level skyscraped and was significantly higher than any other group." (PMID 29131464, 2018). "The number of double‐positive cells (IRF5+Iba‐1+ or IRF4+Iba‐1+) after stroke was normalized to sham groups." (PMID 29131464, 2018). "Together, these results indicated that neuron-specific IRF4 deletion deteriorates the stroke outcomes." (PMID 24510125, 2014).